RNF113B (ring finger protein 113B)
Synonyms: RNF161; ZNF183L1; bA10G5.1
Tractability: No criterion of Open Targets' tractability assessment is met for any kind of drug.
Gene: Protein-coding gene on chromosome 13 (98,175,785 to 98,177,269, reverse strand). Ensembl gene ENSG00000139797.
Gene Ontology:
Molecular function: ubiquitin-protein transferase activity; metal ion binding
Biological process: mRNA splicing, via spliceosome
Cellular component: U2-type spliceosomal complex
Genetic constraint (gnomAD): Loss-of-function variants: 12 observed, 21.77 expected, observed/expected ratio (o/e) 0.55, 90% interval 0.35 to 0.89. The upper end of that interval is the gene's LOEUF score, 0.89, which puts it in group 3 of 6, group 1 being the genes least tolerant of losing a copy. Missense variants: 441 observed, 450.64 expected, observed/expected ratio (o/e) 0.98, 90% interval 0.9 to 1.06. Synonymous variants: 193 observed, 182.51 expected, observed/expected ratio (o/e) 1.06, 90% interval 0.94 to 1.19.
Homologues: Orthologues: chimpanzee RNF113B (99% identical), macaque RNF113B (91% identical), dog RNF113A (73% identical), tropical clawed frog rnf113a (57% identical), zebrafish rnf113a (57% identical), Drosophila melanogaster mdlc (48% identical), Caenorhabditis elegans rnf-113 (41% identical). Paralogues in human: RNF113A (73% identical).
Diseases named in the same sentence as RNF113B in open-access papers:
RNF113B is named in the same sentence as 2 diseases in open-access papers, as found by Europe PMC text mining. Sharing a sentence is not in itself a finding about the gene and the disease. The quoted sentences say what the papers report.
Infertility (1 paper, 2024). "More specifically, by analyzing our in-house whole exome database containing sequencing data from 74 cases of human male meiotic arrest, we identified an infertile man harboring a homozygous loss of function (LoF) variant in a human paralog (RNF113B)." (PMID 39388236, 2024). "Thus, we harnessed the sizeable effect of RNF113B on this network as a means of identifying additional genetic causes of human infertility." (PMID 39388236, 2024). "In summary, by experimentally disrupting the male germ cell orthoBackbone across evolutionarily distant species, we were able to uncover two new candidate genes for human infertility (HSPA2 and KPNA2) in addition to RNF113B, affecting a combined total of five individuals." (PMID 39388236, 2024).
male infertility (1 paper, 2024). The inability of the male to effect fertilization of an ovum after a specified period of unprotected intercourse. "The translational application of our cross-species platform in human reproductive healthcare has so far uncovered three new genes associated with human male infertility (RNF113B, HSPA2, and KPNA2)." (PMID 39388236, 2024).